CEBPG (CCAAT enhancer binding protein gamma)
Description:
Transcription factor that binds to the promoter and the enhancer regions of target genes. Binds to the enhancer element PRE-I (positive regulatory element-I) of the IL-4 gene. Binds to the promoter and the enhancer of the immunoglobulin heavy chain. Binds to GPE1, a cis-acting element in the G-CSF gene promoter.
Synonyms: GPE1BP; IG/EBP-1
Tractability: PROTAC: UniProt records ubiquitination sites on it; ubiquitination databases record sites on it.
Gene: Protein-coding gene on chromosome 19 (33,373,685 to 33,382,686, forward strand). Ensembl gene ENSG00000153879.
Subcellular location: Nucleus
Subcellular location (Human Protein Atlas): Nucleoplasm
Pathways (Reactome):
Cellular responses to stimuli: ATF4 activates genes in response to endoplasmic reticulum stress; Response of EIF2AK1 (HRI) to heme deficiency; Response of EIF2AK4 (GCN2) to amino acid deficiency
Gene Ontology:
Molecular function: DNA binding; DNA-binding transcription activator activity, RNA polymerase II-specific; DNA-binding transcription factor binding; protein binding; sequence-specific DNA binding; sequence-specific double-stranded DNA binding; DNA-binding transcription factor activity, RNA polymerase II-specific; RNA polymerase II cis-regulatory region sequence-specific DNA binding; transcription corepressor activity; DNA-binding transcription factor activity; identical protein binding
Biological process: positive regulation of DNA repair; positive regulation of transcription by RNA polymerase II; regulation of transcription by RNA polymerase II; B cell differentiation; enucleate erythrocyte differentiation; immune response; integrated stress response signaling; liver development; natural killer cell mediated cytotoxicity; positive regulation of type II interferon production; DNA-templated transcription; negative regulation of transcription by RNA polymerase II; regulation of DNA-templated transcription
Cellular component: nucleoplasm; RNA polymerase II transcription regulator complex; chromatin; nucleus
Genetic constraint (gnomAD): Loss-of-function variants: 7 observed, 12.26 expected, observed/expected ratio (o/e) 0.57, 90% interval 0.32 to 1.07. The upper end of that interval is the gene's LOEUF score, 1.07, which puts it in group 4 of 6, group 1 being the genes least tolerant of losing a copy. Missense variants: 161 observed, 194.42 expected, observed/expected ratio (o/e) 0.83, 90% interval 0.73 to 0.94. Synonymous variants: 66 observed, 74.02 expected, observed/expected ratio (o/e) 0.89, 90% interval 0.73 to 1.09.
Homologues: Orthologues: chimpanzee CEBPG (99% identical), macaque CEBPG (99% identical), rabbit CEBPG (95% identical), rat Cebpg (93% identical), dog CEBPG (91% identical), mouse Cebpg (91% identical), pig CEBPG (87% identical). Paralogues in human: CEBPE (32% identical), CEBPA (31% identical), CEBPB (31% identical), CEBPD (31% identical).
Diseases named in the same sentence as CEBPG in open-access papers:
CEBPG is named in the same sentence as 34 diseases in open-access papers, as found by Europe PMC text mining. Sharing a sentence is not in itself a finding about the gene and the disease. The quoted sentences say what the papers report.
ovarian carcinoma (11 papers, 2021 to 2026). A malignant neoplasm originating from the surface ovarian epithelium. "In contrast, CEBPG has been found to inhibit apoptosis in ovarian cancer cells, thereby promoting tumor progression and directly enhancing cancer cell proliferation and migration across multiple tumor types." (PMID 41614948, 2026). "The knockdown of CEBPG inhibited the proliferation and invasion of A2780 and Hey ovarian cancer cells, promoting ferroptosis." (PMID 38203758, 2024). "An interesting study found that CEBPG expression was increased in ovarian cancer tissues compared to normal ovarian tissues and was also associated with a poor prognosis." (PMID 38203758, 2024). "In summary, we found that CEBPG promoted ovarian tumor cell proliferation and inhibited ferroptosis in vitro and accelerated tumor growth in vivo, and the promotion of ovarian cancer by CEBPG is partially dependent on SLC7A11." (PMID 37210575, 2023). "Interestingly, CEBPG knockdown in A2780 and Hey ovarian cancer cells significantly decreased GPX4 and SLC7A11 expression." (PMID 38203758, 2024). "Moreover, CCAAT/enhancer-binding protein gamma (CEBPG) was established as a novel transcriptional modulator of ferroptosis in ovarian cancer, regulating ferroptosis via transcriptional control of SLC7A11." (PMID 37840106, 2023). "In view of this, we speculated that CEBPG promoted the metastasis of ovarian cancer cells in part by regulating the Epithelialmesenchymal transition (EMT) pathway." (PMID 37210575, 2023). "Moreover, circFoxp1 could regulate the expression of FMNL3 (formin like 3) and CEBPG (CCAAT enhancer binding protein gamma) in ovarian cancer." (PMID 38152652, 2023). "Furthermore, in ovarian cancer, circFOXP1 regulates miR-22 and miR-150-3p through a sponge mechanism, positively influencing the expression of CEBPG and FMNL3, thereby promoting both cancer cell proliferation and enhancing the sensitivity of epithelial ovarian cancer cells to cisplatin." (PMID 39606233, 2024). "In addition, important cellular modulators, such as non-coding RNAs, Ets-1, CEBPG, ARID1A, SNAI2 and HRD1, could significantly regulate SLC7A11 expression in ovarian cancer cells, suggesting that these modulators could be potential therapeutic targets in ovarian cancer patients." (PMID 38203758, 2024).
acute myeloid leukemia (5 papers, 2017 to 2023). Acute myeloid leukemia (AML) is a group of neoplasms arising from precursor cells committed to the myeloid cell-line differentiation. "For instance, CEBPG deregulation could result in the differentiation arrest of malignant cells in acute myeloid leukemia." (PMID 37210575, 2023). "Additionally, CEBPG acts as a regulator gene for the progression of many types of cancer, such as acute myeloid leukemia, lung cancer, and esophageal cancer." (PMID 37210575, 2023).
breast carcinoma (3 papers, 2013 to 2025). "In addition, we also detected the effects of 15 TFs on the proliferation function of breast cancer cells, among which knockdown of SOX6, SOX15, or CEBPG significantly inhibited the proliferation of Hs578T and BT549 cells, respectively." (PMID 40397381, 2025).
esophageal squamous cell carcinoma (3 papers, 2021 to 2023). Esophageal squamous cell carcinoma (ESCC) is a type of esophageal carcinoma (EC) that can affect any part of the esophagus, but is usually located in the upper or middle third. "For example, it is reported that CEBPG significantly promotes the proliferation and migration of esophageal squamous cell carcinoma (ESCC) cells, and is thus suggested as a prognostic factor for patients with ESCC." (PMID 34743716, 2021).
lung carcinoma (2 papers, 2017 to 2023). "Further, we previously reported that a set of AO, DNAR, and CCC genes containing CEBPG recognition sites display transcript abundance correlation with CEBPG, consistent with regulation by CEBPG, and also display lung cancer-associated expression patterns in NBEC." (PMID 28464886, 2017). "Moreover, CEBPG has been suggested to be a biomarker for lung cancer risk." (PMID 37210575, 2023). "Thus, it is reasonable to speculate that inter-individual variation in CEBPG expression combined with variation in ERCC5 cis-regulatory SNPs contributes to lung cancer risk determination through effect on regulation of one or both of the alternative ERCC5 transcripts." (PMID 28464886, 2017).
psoriasis (2 papers, 2024 to 2025). An autoimmune condition characterized by red, well-delineated plaques with silvery scales that are usually on the extensor surfaces and scalp. "The study suggests that the CEBPG gene at a newly reported psoriasis risk locus (19q13.11), is predicted by TWAS to be downregulated in the presence of psoriasis risk variants, corroborating previous reports of C/EBPγ suppression of proinflammatory cytokines." (PMID 38785955, 2024).
colorectal cancer (1 paper, 2024). A primary or metastatic malignant neoplasm that affects the colon or rectum. "Among the top ten more active transcription factors in left-sided colorectal cancer we found a significant enrichment of transcription factors associated with unfolded protein response (NFYA and CEBPG, hypergeometric test, FDR < 0.01)." (PMID 38438786, 2024).
coronary heart disease (1 paper, 2022). "CA9, CBS, CEBPG, HSPB1, SLC1A4, HSPB1 and TRIB3 are genes that we have screened for iron death in coronary heart disease samples." (PMID 35152560, 2022).
dilated cardiomyopathy (1 paper, 2022). Cardiomyopathy which is characterized by dilation and contractile dysfunction of the left and right ventricles. "Besides, we also found that CEBPG was closely related to the ‘Regulation of actin cytoskeleton’ (also enriched in SLC1A4, STMN1 and CBS), ‘Vascular smooth muscle contraction’, ‘Dilated cardiomyopathy’, ‘Relaxin signalling pathway’, ‘Cardiac muscle contraction’ and ‘Hypertrophic cardiomyopathy’." (PMID 35152560, 2022).
heroin addiction (1 paper, 2016). "Our classification analysis identified JUN, CEBPG, ENO2, and PRKCB as the key gene expression signatures for a subdivision of heroin dependence and controls." (PMID 27495086, 2016).
inflammatory bowel disease (1 paper, 2017). A spectrum of small and large bowel inflammatory diseases of unknown etiology. "Several IEC signature TFs have known associations with human Inflammatory Bowel Diseases (IBD), including SMAD7, CEBPG, STAT3, XBP1, HNF4A, ELF3, IRF1, and NFκB components IKBKB, IKBKG, and NFKBIZ." (PMID 28850571, 2017).
leukemia (1 paper, 2023). A malignant (clonal) hematologic disorder, involving hematopoietic stem cells and characterized by the presence of primitive or atypical myeloid or lymphoid cells in the bone marrow and the blood. "Most of the genes in the HIF1A module play leukemia-promoting roles in AML, such as HIF1A, CEBPG, JUN, and ATF4." (PMID 37691822, 2023).
metastatic cancer (1 paper, 2020). A carcinoma which has spread from the original site of growth to another anatomic site. "In primary or metastatic cancer, mRNAs IGF2BP3, HOXA9, HOXA10, CEBPG competed with HOXA11-AS mutually, and HOXA10 as well as IGF2BP3 were also continuously up-regulated among normal-primary-metastatic process with significant difference in variance analysis." (PMID 33614509, 2020).
metastatic tumor (1 paper, 2023). "In addition, when compared with primary OC tissues, CEBPG expression was also elevated in peritoneal metastatic tumor tissues." (PMID 37210575, 2023).
myeloma (1 paper, 2010). "Interestingly, in LP-1D1b cells, we noticed the up-regulation of CEBPG (FC: +3.08), coding for a close related transcription factor C/EBPγ whose function in myeloma cells remains to be established." (PMID 20459741, 2010).
Oral Squamous Cell Carcinoma (1 paper, 2026). "Significance: Palmitic acid promotes metastasis via a stromal CEBPG-IRE1α/TMBIM6 axis, uncovering a metabolic vulnerability that offers novel therapeutic targets to inhibit oral squamous cell carcinoma." (PMID 42227941, 2026).
osteoporosis (1 paper, 2023). A condition of reduced bone mass, with decreased cortical thickness and a decrease in the number and size of the trabeculae of cancellous bone (but normal chemical composition), resulting in increased fracture incidence. "The network based on hub genes showed that 3 TFs (TRIM22, CEBPG, and CEBPZ), 4 miRNAs (hsa-miR-132-3p, hsa-miR-182-5p, hsa-miR-212-3p, and hsa-miR-324-5p), and 4 drugs were involved in osteoporosis." (PMID 38260098, 2023).
periodontitis (1 paper, 2024). An acute or chronic inflammatory process that affects the tissues that surround and support the teeth. "The results showed that the six transcriptional biomarkers were closely associated with multiple immune cells in periodontitis samples, particularly TFAP2C, CEBPG, and BNIP3." (PMID 39045324, 2024). "LURAP1L and RGS4 showed significant overexpression, whereas ALOX12B, BNIP3, CEBPG, and TFAP2C were notably underexpressed in periodontitis." (PMID 39045324, 2024). "Secondly, our study identified six transcripts that are tissue biomarkers for periodontitis (ALOX12B, BNIP3, CEBPG, LURAP1L, RGS4, and TFAP2C) potentially significant for periodontitis using three machine learning methods: LASSO, SVM, and RF." (PMID 39045324, 2024). "The results derived from the three machine learning methods were intersected and illustrated in a Venn diagram, revealing six transcriptional biomarkers critical for differentiating periodontitis tissues from healthy tissues: ALOX12B, BNIP3, CEBPG, LURAP1L, RGS4, and TFAP2C." (PMID 39045324, 2024).
cancer (16 papers, 2009 to 2026). A tumor composed of atypical neoplastic, often pleomorphic cells that invade other tissues. "Previous studies have implicated CEBPG as an antioxidant regulator that controls redox homeostasis in normal and cancer cells." (PMID 35633787, 2022). "Comprehensive transcriptomic and proteomic evaluations across a spectrum of cancer types divulged a marked upregulation of CEBPG, notably within GBM instances." (PMID 39707474, 2024). "In recent years, CEBPG hyperactivation has been reported in numerous studies as a factor contributing to the progression of cancer; however, the exact mechanism of CEBPG remains a mystery in OC." (PMID 37210575, 2023). "Recently, CEBPG has gained considerable attention as a potential molecular marker for cancer progression and as a therapeutic target." (PMID 37210575, 2023). "For instance, CEBPG, a TF that promotes cancer development by enhancing the PI3K–Akt signaling pathway, was found to be robustly more active in tumor cells than in other cells." (PMID 36155797, 2022). "Although the roles of CEBPG in several types of cancer have been revealed, its expression profile and molecular functions in AML remain unresolved." (PMID 34743716, 2021). "Thus, CEBPG favors cancer progression by inhibiting ferroptosis through an increase in SLC7A11 expression." (PMID 38203758, 2024). "CEBPG is an important regulator in tumor development and is highly expressed in cancer cells." (PMID 38203758, 2024). "Using the public transcriptomic dataset, the Cancer Cell Line Encyclopedia (CCLE) and western blotting, we also found that CEBPG was overexpressed in AML." (PMID 34743716, 2021). "CCAAT enhancer binding proteins (CEBPs) including CEBPA, CEBPB, CEBPD, CEBPE, CEBPG and CEBPZ, are suggested as potential biomarkers for cancer prognosis." (PMID 34743716, 2021). "Using the public transcriptomic dataset, the Cancer Cell Line Encyclopedia (CCLE) and western blotting, we also found CEBPG was overexpressed in AML." (PMID 34743716, 2021). "The expression of CEBPG and RUNX1 proteins in the cancer tissues was significantly higher than that in the adjacent tissues (P < 0.05)." (PMID 32655621, 2020). "Alternatively, increased expression of CEBPG and SMAD5, transcription factors with known roles in cancer cell metastasis via Hippo and BMP pathways respectively, suggests roles for additional signaling events in modulating the invasive behavior of SW-13 cells." (PMID 29884238, 2018). "Most notably, meticulous analysis proved that circFoxp1 on exosomes can inhibit miR-22 and miR-150-3p, leading to increased expression of two genes, CCAAT enhancer binding protein gamma (CEBPG) and formin-like 3 (FMNL3), which may affect the resistance of cancer cells to cisplatin." (PMID 36139487, 2022).
tumor (9 papers, 2018 to 2026). "As a result, further investigation was conducted to explore the association between CEBPG and tumor development in GBM." (PMID 39707474, 2024). "After verifying the specific expression and tumor-promoting functions of CEBPG in the MES-like GBM in vitro, we further confirmed these findings in human GBM samples." (PMID 39707474, 2024). "As shown in the orthotopic ovarian tumorigenesis assay, knockdown of CEBPG significantly reduced tumor growth in nude mice." (PMID 37210575, 2023). "Mechanistically, the results of CUT&Tag and luciferase reporter assays showed that CEBPG inhibited ferroptosis of tumor cells by upregulating SLC7A11, a negative regulator of ferroptosis, thus accelerating the progression of OC." (PMID 37210575, 2023). "CEBPG, on the other hand, was significantly upregulated in the tumor samples of both datasets when compared to the control samples." (PMID 36675048, 2023). "In vivo, CEBPG knockdown–induced inhibition of xenograft tumor growth was also significantly rescued by SLC7A11 restoration, consistent with that in vitro." (PMID 37210575, 2023). "CEBPG is an important regulator in tumor development, yet it is unclear exactly how it contributes to the progression of OC." (PMID 37210575, 2023). "In addition, CEBPG functioned as a key regulatory factor that increased tumor malignancy through BCL2L1-mediated survival pathways to some extent." (PMID 41958675, 2026). "However, while multiple studies have revealed CEBPG’s role in promoting tumor growth, there is still a great deal of uncertainty about its role in OC." (PMID 37210575, 2023). "Moreover, we extracted protein and RNA from these tumor tissues to examine the expression levels, the results of Western Blotting and qRT-PCR showed that knockdown of CEBPG in mice also reduced the expression of SLC7A11." (PMID 37210575, 2023). "Furthermore, transcription factor analysis suggested that CEBPG might regulate BCL2L1 expression to promote tumor survival and migration." (PMID 41958675, 2026). "This validates our previous findings that CEBPG is significantly enriched in hypoxic pathways, enhancing GBM cell resistance to hypoxia and increasing their adaptive capacity in hypoxic tumor conditions." (PMID 39707474, 2024). "Then, we analyzed the levels of CEBPG and SLC7A11 in these orthotopic tumor tissues by IHC staining." (PMID 37210575, 2023). "Mechanistically, RNA sequencing results suggest LCFAs may primarily suppress tumor progression through the transcriptional regulation of MSX1, CEBPG, and NR2F2." (PMID 41614948, 2026). "Thus, C/EBPγ is generally perceived as a tumor promoter and the observation that CEBPG mRNA is upregulated in tumor as opposed to normal PDAC tissue encourages this impression." (PMID 36675048, 2023).
infection (2 papers, 2022 to 2024). The state of being infected such as from the introduction of a foreign agent such as serum, vaccine, antigenic substance or organism. "Here, the CEBPG gene was upregulated in CCC as result of infection." (PMID 35873155, 2022).
CEBPG also shares sentences with these, for which no sentence is quoted: bladder cancer (2 papers); diabetes mellitus (1); Epstein-Barr virus infection (1); esophageal cancer (1); Glucose intolerance (1); head and neck squamous cell carcinoma (1); hepatoma (1); hypertrophic cardiomyopathy (1); lung fibrosis (1); malaria (1); melanoma (1); ovarian tumor (1); vitiligo (1).